MIR3135A (microRNA 3135a)
Synonyms: hsa-mir-3135; MIR3135; hsa-mir-3135a
Gene: MicroRNA gene on chromosome 3 (20,137,565 to 20,137,641, forward strand). Ensembl gene ENSG00000266745.
Homologues: Orthologues: chimpanzee MIR3135A (100% identical).